LINC00200 (long independently transcribed non-coding RNA 200)
Synonyms: FLJ40354; C10orf139; NCRNA00200
Gene: Long non-coding RNA gene on chromosome 10 (1,159,768 to 1,289,426, forward strand). Ensembl gene ENSG00000229205.
Diseases named in the same sentence as LINC00200 in open-access papers:
LINC00200 is named in the same sentence as 6 diseases in open-access papers, as found by Europe PMC text mining. Sharing a sentence is not in itself a finding about the gene and the disease. The quoted sentences say what the papers report.
gastric cancer (1 paper, 2022). A primary or metastatic malignant neoplasm involving the stomach. "There are studies suggested that LINC00200 could be used as a candidate molecular marker for the diagnosis of gastric cancer, and new insights were subsequently provided for gastric cancer treatment." (PMID 36105104, 2022).
hepatocellular carcinoma (1 paper, 2020). A malignant tumor that arises from hepatocytes. "They reported that LINC00200 played a critical part in early stage hepatocellular carcinoma (HCC) after analyzing RNA-sequencing expression data of liver cancer from the TCGA and GEO database." (PMID 33344459, 2020).
renal clear cell carcinoma (1 paper, 2020). "In our study, high expression of LINC00200 was associated with poor survival outcomes in KIRP patients and higher expression of LINC00200 at later tumor stages, which indicated that LINC00200 may have been an oncogene in renal clear cell carcinoma." (PMID 33344459, 2020).
tumor (1 paper, 2020). "Upon searching for these genes on PubMed, we found that they had been studied for their association with tumor progression as well as their mechanisms, if action with the exception of LINC00200." (PMID 33344459, 2020).
LINC00200 also shares sentences with these, for which no sentence is quoted: cancer (1 paper); liver cancer (1).